MIF (macrophage migration inhibitory factor)
Diseases named in the same sentence as MIF in open-access papers (continued):
Sharing a sentence is not in itself a finding about the gene and the disease.
cancer (continued). "Together, the complexities of MIF-associated functions in cancer highlight the importance of understanding novel aspects of MIF biology." (PMID 26741693, 2016). "MIF is a pleiotropic proinflammatory cytokine that plays a causative role in multiple diseases, including cancer." (PMID 26530123, 2015). "MIF is a pro-inflammatory cytokine which plays a key role in innate and adaptive immunity and is associated with inflammatory conditions including cancer." (PMID 26530123, 2015). "MIF was also found to be highly produced by cancer associated fibroblasts isolated from human tumors compared to fibroblasts from matched normal tissues from uninvolved areas." (PMID 24887129, 2014). "We believe ISO-66 offers promise as a MIF-reducing therapy in cancer and other MIF-implicated diseases." (PMID 25050663, 2014). "Since chronic inflammation is a risk factor for tumorigenesis in these cancers, in this study, the role of MIF in pro-tumorigenic events was examined." (PMID 24887129, 2014). "High MIF levels were found in the tumors and sera of patients with different types of cancer, and MIF production has been consistently associated with the aggressiveness and metastatic potential of human tumors." (PMID 23497377, 2013). "Since increased plasma MIF levels are associated with cancer, studies have examined the association between Mif promoter polymorphisms and cancer." (PMID 22168770, 2011). "Constitutive activation of the BMP pathway and the expression of MIF have been linked to a variety of cancers." (PMID 20100315, 2010). "Although MIF is associated with cancer angiogenesis, progression, and metastasis, the exact mechanism of this cytokine's action is uncertain since a receptor for MIF has only recently been identified as the cell surface form of the invariant chain (CD74)." (PMID 16000172, 2005). "Blocking MIF reversed cancer-associated fibroblast-driven invasion and angiogenesis." (PMID 42003920, 2026). "While much is known about MIF signaling in conventional cancers, there is limited data on the role of MIF signaling activation in virus-associated cancers, including how oncoviruses may regulate MIF signaling." (PMID 41472252, 2025). "In the context of cancer, MIF is intricately linked to the development and progression of KIRC." (PMID 39031800, 2024). "Moreover, functional studies have also interrogated the multitude of cancer-related phenotypes associated with MIF, including cell survival/death, invasion, angiogenesis, and immune suppression." (PMID 39233830, 2024). "Cancer-associated fibroblasts provide an immunosuppressive microenvironment via MIF signaling." (PMID 37649598, 2023). "Transcriptome analysis also provided evidence for the role of MIF in cancer-associated pathways." (PMID 36703790, 2022). "Patients with chronic tissue injury already have an increased risk of developing cancer and thereby treatment of tissue injury with MIF or D-DT may be a double-edged sword." (PMID 35091838, 2022). "MIF loss in Pol δ−proficient MDA-MB-231 cancer cells significantly reduced cell proliferation." (PMID 34012010, 2021). "Of note, MIF has been implicated in tissue hypoxia and its expression and secretion has been shown to be induced by hypoxia in various cell types including endothelial cells and cancer cells." (PMID 34366876, 2021). "Investigations have recognized MIF as a central participant in the cancer-associated immune response, having the capacity to support the development of HNSCC by its pleiotropic roles in mediating hypoxia response, angiogenesis, and epithelial-mesenchymal transition (EMT)." (PMID 35047982, 2020). "It is a well-known fact that MIF is implicated in angiogenesis in many cancers." (PMID 31013837, 2019). "Intriguingly, MIF is a classical pro-survival cytokine, meaning that its downregulation may also contribute to the lower tumorigenic potential of the CI-deficient cancer cells." (PMID 30796225, 2019).
cancer (continued). "Moreover, MIF has been broadly implicated in cancer, with overexpression shown in a number of solid tumor types." (PMID 29864117, 2018). "MIF levels are associated with an increased incidence of a large number of cancer types." (PMID 28957348, 2017). "In addition to the pathogenic roles of MIF in acute infection, MIF is also essential for the pathogenesis of chronic diseases, such as autoimmune and cardiovascular diseases, as well as cancer." (PMID 25821355, 2015). "Unregulated cell proliferation remains a hallmark of cancer, and given the known stimulation of several central pro-proliferation pathways MIF induces upon binding to CD74, further investigation into the role of MIF in inflammation-associated cancers is warranted." (PMID 24887129, 2014). "Other groups have also started to suggest that MIF may have diagnostic and prognostic value in inflammation-associated cancers." (PMID 24887129, 2014). "MIF, a lymphokine involved in cell-mediated immunity and inflammation, is implicated in cancer." (PMID 24084722, 2013). "Similarly, studies examining the association between Mif promoter polymorphisms and cancer have reported an increased risk of cancer for patients with higher MIF protein producing promoter genotypes while others have reported a lack of association." (PMID 22168770, 2011). "Although the specificity of MIF is not as high as that of CEA (90.6% vs. 100.0%), MIF is more sensitive during early cancer detection (47.3% vs. 29.5%), which suggests that MIF may be used as a diagnostic marker in CRC." (PMID 20957089, 2010). "Overexpression of MIF has been implicated in several cancers." (PMID 17650334, 2007). "However, its role in virus-associated cancers or how oncoviruses may regulate MIF signaling activities remains largely unknown." (PMID 41472252, 2025). "MIF may be implicated in certain forms of tumorigenesis as suggested by genetic studies showing that the single nucleotide polymorphism (SNP) -173 G/C (rs755622) on MIF gene is associated to MIF hyperproduction and correlates with cancer." (PMID 32155795, 2020). "Moreover, findings that MIF is involved in critical pro-survival signalling pathways together with cell cycle control has provided interest in possible associations with the development and progression of cancer." (PMID 25168062, 2014). "These fibroblasts interact with maEpCs and endothelial cells via ligands such as MIF, promoting epithelial-mesenchymal transition, cancer stemness, and angiogenesis." (PMID 42003920, 2026). "In parallel with CD74-targeted cancer therapies, humanized monoclonal antibodies that neutralize MIF itself are also under development." (PMID 41597203, 2026). "Spatial analysis revealed there was more distant proximity between TAMs and CD44+ cancer cells upon MIF inhibition." (PMID 41545340, 2026). "In terms of cancer cell stemness, MIF inhibition in MASLD led to a reduction in CD44+ or ALDH+ or CD44+/KLF4+ cancer cells." (PMID 41545340, 2026). "In vivo studies using constitutive mouse models further support MIF’s role in cancer progression, with evidence from breast, skin, pancreas, intestine, and bladder cancers." (PMID 40835826, 2025). "MIF, an immunoregulatory cytokine, plays multiple roles in the pathogenesis of cancer and inflammation." (PMID 40835826, 2025). "In other cases, CD74 expression was shared between stromal and malignant epithelial cells, hinting at MIF’s involvement in autocrine regulation of angiogenic factors or inhibition of apoptosis in cancer cells." (PMID 41159021, 2025).
cancer (continued). "Consistent with previous report in various cancer types, MIF targeting reduced M2-like polarization and increased the proportion of M1-Ctrl and M1-like PDL1high macrophages." (PMID 41310721, 2025). "This supports the concept of targeting epithelial MIF as a cancer-selective vulnerability with significant therapeutic potential." (PMID 40835826, 2025). "For example, central genes such as macrophage migration inhibitor (MIF), showed significant alterations in DM patients with cancer." (PMID 39906519, 2025). "In MDA-MB-231 cells, MIF acts in a chemokine-like manner to facilitate movement through basement membrane-like layers, suggesting that MIF produced in the TME contributes to cancer invasiveness." (PMID 41159021, 2025). "For example, immunosuppressive interactions involving the PGE2, MIF and midkine (MK) gene products were more likely between cancer basal cells and CD4+ and CD8+ T cells in the older cohort." (PMID 41188599, 2025). "Its ability to interfere with MIF’s negative regulation of apoptosis further supports its potential use in cancer treatment by promoting cell death while inhibiting proliferation pathways." (PMID 41159021, 2025). "This was characterized by high expression of macrophage migration inhibitory factor (MIF) in cancer cells, which signaled to B cells expressing the CD74 and CXCR4 receptors." (PMID 41249133, 2025). "Macrophage migration inhibitory factor (MIF), an upstream immunoregulatory cytokine, has emerged as a potential target due to its multifaceted role in cancer pathogenesis." (PMID 40835826, 2025). "Through the activation of MIF‐related pathways, luminal cells are in a highly cyclical state, and the extent of oxidative phosphorylation is significantly increased to induce cancer cell growth." (PMID 40857024, 2025). "Activation of MAPK and PI3K pathways by MIF regulated fundamental cellular functions related to proliferation, differentiation, apoptosis, cell survival, and cancer development." (PMID 40936936, 2025). "Our studies show that FOS is a main regulator of C0 MAFF+ TCs in LUAD, polarizing macrophages via MIF and rewiring lipid metabolism to support cancer." (PMID 40936936, 2025). "In cancer biology, MIF and its downstream signaling pathways promote cancer cell survival, growth, and immune evasion." (PMID 41472252, 2025). "Numerous studies have demonstrated remarkable overexpression of MIF in several types of human cancer 25-29." (PMID 40092701, 2025). "Above all, majority of studies have shown that elevated CCL4 and MIF play a promoting role in cancer developments and progression." (PMID 40092701, 2025). "Although our MR framework supports causal inference, the precise biological mechanism underlying observed immune–cytokine–cancer interactions (e.g., BAFF-R/MIF crosstalk) requires experimental validation using preclinical models." (PMID 41292522, 2025). "Macrophage migration inhibitory factor (MIF) signaling activation has been found closely related to many cancer cell malignant behaviors and infectious disease progression." (PMID 41472252, 2025). "Elevated MIF levels have been shown in various human cancer entities such as breast, ovary, colon, prostate, liver, lung, pituitary and brain." (PMID 40835826, 2025). "More significant MIF signal sending capacity was demonstrated by high-riskscore cancer cells, indicating the stronger immune microenvironment regulatory ability." (PMID 41200185, 2025). "In the MIF signaling pathway, both high- and low-riskscore cancer cells regulated macrophage function and polarization states through MIF secretion." (PMID 41200185, 2025). "Several cancers are characterized by overexpression of MIF which contributes to immune evasion, tumor growth and angiogenesis, and metastasis." (PMID 40092999, 2025). "MIF not only supports cell growth but also promotes the migration and invasion of cancer cells in a dose-dependent manner." (PMID 41159021, 2025).
cancer (continued). "This paracrine MIF–CD74/CD44 interaction is a well-recognized mechanism of immunosuppression in the TME: MIF is often overexpressed in cancers and can drive macrophages toward an “M2” immunosuppressive, pro-tumoral phenotype." (PMID 40740766, 2025). "Recent studies have shown that cancer-associated fibroblasts (CAFs) influence the metabolic activity of MDSCs through CD36 and the secretion of macrophage migration inhibitory factor (MIF), further exacerbating immune evasion." (PMID 40901479, 2025). "Pertinent to this area of study, multiple MIF modulators are currently being investigated as targets for anti-cancer treatment." (PMID 38730725, 2024). "In murine models, combined CD36 and PD-L1 inhibition restored an antitumor immune signature in the TME, further validating the role of MIF in cancer progression." (PMID 38732068, 2024). "Like TNBC, MIF signaling between cancer luminal A cells and CD4+ or CD8+ T cells via CD74 complexes was elevated in the older cohort." (PMID 39483921, 2024). "Studies have shown increased concentrations of multiple cytokines, including interleukin 6, TNFα, interleukin 8, the cytokines MIF, TGFβ, interleukin 10 and interleukin 18 in patients with cancer." (PMID 39020272, 2024). "As a pleiotropic protein, MIF plays an important role in cancer growth, inflammation, and immune response by activating the signaling pathways of the CD74 and CXC chemokine receptors." (PMID 38924362, 2024). "MIF is released by several cells comprising macrophages, granulocytes, T and B lymphocytes, endothelial cells, as well as cancer cells." (PMID 38916819, 2024). "This phenomenon underlines the possible reasons for the poor efficacy of a single anti-CSF1 or MIF in cancer treatment." (PMID 39323622, 2024). "MIF and CD74 have been implicated in the mechanisms of the development of various cancers, including non-small-cell lung cancer, prostate cancer, head and neck squamous cell carcinoma, and brain tumors." (PMID 38730725, 2024). "While SLC2A11 plays a crucial role in glucose absorption and is commonly observed in cancer cells due to its high energy demand, and MIF is involved in cell proliferation, tumorigenesis, and metastasis across multiple cancers." (PMID 39156764, 2024). "As a pro-inflammatory cytokine, macrophage migration inhibitory factor (MIF) accelerated deleterious inflammation and promoted cancer metastasis and progression." (PMID 38529274, 2024). "Despite this potential, anti-cancer drugs that target MIF (Imalumab: NCT01765790) and SPP1(BET inhibitors) are still in the exploratory or early clinical trial phase." (PMID 38191424, 2024). "Macrophage migration inhibitory factor (MIF) has been shown to promote cancer cell proliferation and metastasis by activating multiple signaling pathways." (PMID 38951896, 2024). "Continuing with advancements in cancer treatment, a hydrogel incorporating gold nanorods (AuNRs) and macrophage migration inhibitory factor (MIF) inhibitors was developed for combined photothermal and immune therapy." (PMID 38675454, 2024). "It was demonstrated that the use of glucan NPs containing siRNA targeting MIF (macrophage migration inhibitory factor) inhibits 4T1 cancer cells." (PMID 39795985, 2024). "Based on the importance of MIF in normal homeostasis and its alterations in pathological conditions such as cancer, there have been several classes of drugs developed against MIF." (PMID 39233830, 2024). "In another study, it was shown that macrophage migration inhibitory factor (MIF) is mainly produced by cancer stem-like cells and attracts MDSCs." (PMID 38786032, 2024). "In tumorigenesis, MIF-CD74 interactions are known to promote tumor cell growth and survival, with the expression levels of MIF being closely tied to tumor aggressiveness and prognosis in certain types of cancer." (PMID 38711918, 2024). "By targeting MIF, eugenol has the potential to inhibit key cellular processes in cancer cells that contribute to cancer cell growth." (PMID 39416730, 2024).
cancer (continued). "Anti-MIF (imalumab) completed phase II testing in heavily pre-treated cancer patients with a favorable safety profile, but has yet to be evaluated further." (PMID 38178143, 2024). "MIF and DDT dysregulation have been implicated in most of the pathologic hallmarks of cancer, with downstream effects of proliferation, immune suppression, immune dysregulation, enhancement of angiogenesis and metastasis." (PMID 39028303, 2024). "Given substantial data for roles for MIF and DDT in preclinical cancer models, we encourage continued exploration of clinical and patient-derived models to further evaluate MIF and DDT as effective antitumor targets." (PMID 38732068, 2024). "Consistently, we confirmed that inhibition MIF in cancer cells and CD74 in microglia promoted M1 polarization, showing upregulated level of CD86 fluorescence intensity and proportion of CD86 + cells." (PMID 38685050, 2024). "By producing macrophage migration inhibitory factor (MIF), immunosuppressive microfibril-associated protein 2 (MFAP2+) cancer-associated fibroblasts (CAFs) can interact with T cells, B cells, and macrophages." (PMID 38928662, 2024). "MIF is overexpressed in various cancers, including lung cancer, osteosarcoma, metastatic melanoma, and many others; CD74 expression and overexpression are also associated with diverse cancers." (PMID 38730725, 2024). "For example, the intracellular effect of MIF in inhibiting the JNK signaling pathway was observed in cancer cells, but the extracellular effect of MIF in activating JNK through the CD74 receptor was reported in T cells and fibroblasts." (PMID 37935315, 2024). "MDSCs have been identified nearby cancer stem cells (CSC) which are responsible for high MIF production and promotion of immune suppression activities of MDSCs." (PMID 38178143, 2024). "MIF signalling pathway has been identified as a key player in cell‒cell interactions crucial for inflammation and cancer." (PMID 39187937, 2024). "It has also been shown that MIF and CD74 expression are closely associated with patient outcomes in many types of cancer, and it is widely suggested that both molecules are promising candidate therapeutic targets." (PMID 38730725, 2024). "OxMIF is selectively present in the plasma and tissues of patients with inflammatory diseases and in solid tumor lesions, and is increasingly recognized as the isoform responsible for pathological functions of MIF in inflammation and cancer." (PMID 39727487, 2024). "MIF promotes cancer cell proliferation and metastasis by activating various signaling pathways, including ERK, MAPK, and Akt." (PMID 38191424, 2024). "MIF is a key mediator in various immune and inflammatory responses, including diseases such as RA and cancer." (PMID 39614150, 2024). "The aim of this review is to summarize the available information regarding the MIF family in cancer, comprising MIF and DDT." (PMID 36672343, 2023). "Secretion of MIF (macrophage migration inhibitory factor) during NEPC has been shown to facilitate cancer progression and recurrence." (PMID 37761978, 2023). "Several studies have highlighted a relationship between MIF, cancer cells, and the Warburg effect, demonstrating a correlation between high MIF levels and dysregulated cellular energetics." (PMID 36672343, 2023). "Pleural cancer cells interacted with mesothelial cells by MIF/CD74-CD44 complex and AREG/EGFR-ERBB2." (PMID 37649596, 2023). "Here, our study uncovers that MIF secretion is controlled by MYO1B, which provides a mechanism of action as to how MIF is deployed by cancer cells for aggressive progression." (PMID 37611092, 2023). "Cancer cells secrete molecules such as macrophage migration inhibitory factor (MIF), interleukin-8 (IL-8), and plasminogen activator inhibitor-1 (PAI-1) subsequently activating astrocytes." (PMID 37056723, 2023). "From these findings, we infer that MIF can act via two different pathways to promote cancer cell transdifferentiation." (PMID 36672343, 2023).